CDKN2A (cyclin dependent kinase inhibitor 2A)
Diseases named in the same sentence as CDKN2A in open-access papers (continued):
Sharing a sentence is not in itself a finding about the gene and the disease.
tumor (continued). "In this regard, a study over 514 ALM samples identified that these tumours frequently display a dysregulated CDK4 pathway, a product of either gains of CDK4/CCND1 or loss of CDKN2A that, in turn, promote G1 to S cell cycle transition and thus contribute to tumour proliferation." (PMID 32330367, 2021). "Another gene showing promoter hypermethylation in pulmonary carcinoids is CDKN2B, coding for a cyclin-dependent kinase inhibitor p15Ink4b which is functionally similar to the tumor-suppressor gene CDKN2A (encoding for the p16INK4a protein), but less well characterized in its tumorigenic potential." (PMID 33641055, 2021). "Hypermethylation of tumor-related genes, such as cyclin-dependent kinase inhibitor 2A (CDKN2A), E-cadherin (CDH1), death-associated protein kinase (DAPK), phosphatase and tensin homolog (PTEN), and O6-methylguanine-DNA methyltransferase (MGMT), have been reported in HNC." (PMID 34206840, 2021). "In contrast, we observed a strong cytoplasmic expression of P16 in the highly dysplastic region of the CDKN2AWT/#KRASG12DPDAC-like tumor resulting in tumor growth restriction suggesting partial compensation by the heterozygous CDKN2A WT allele upon high oncogenic burden." (PMID 34680288, 2021). "Mutations and deletions of CDKN2A were independently associated with advanced tumour stage in our cohort and some investigators have associated CDKN2A copy number loss with poor prognosis in HNSCC, which was also observed in univariate analysis in our patients." (PMID 33804510, 2021). "Amplification of Telomerase reverse transcriptase (TERT) and loss of cyclin dependent kinase inhibitor 2A/2B (CDKN2A/CDKN2B) detected in the tumor by next gene sequencing suggests that they may play an important role in this case." (PMID 34127009, 2021). "One might speculate that the recently reported age-related increase in the expression of CDKN2A in dogs diminishes a tumor-suppressive function that may account for the higher risk of developing OSA in certain aging dogs." (PMID 34946912, 2021). "Homozygous deletion of P16 can be detected using FISH in both cytological and histological specimens; however, the diagnostic sensitivity for MPM is relatively low at 0.53 (95% CI: 0.35–0.70), despite gene profiling studies demonstrating p16/CDKN2A loss in up to 80% of MPM tumours." (PMID 34209209, 2021). "It is suggested that a germ line mutation in the caspase cleavage site of CDKN2A could increase the susceptibility to neoplasia." (PMID 34711012, 2021). "Commonly mutated genes that characterize PDAC (KRAS and CDKN2A) could be found in both tumor samples." (PMID 33764904, 2021). "The authors concluded that transformation to a premalignant state is driven by increasing CDKN2A/B deficiency, and the tumor with the homozygous deletion defined a category now called “atypical neurofibromatous neoplasms of uncertain biologic potential” (ANNUBP)." (PMID 32642732, 2020). "Therefore, CDKN2A/2B encodes tumor suppressors capable of inducing cell cycle arrest in G1 and G2 phases." (PMID 33335285, 2020). "Similarly, in HNSC the majority of mutations targeting CDKN2A are in the HPV-negative tumor sub-type." (PMID 32242058, 2020). "We also analyzed the prognostic relevance of CDKN2A in IDH-mutated tumor cases." (PMID 33228806, 2020). "Currently, the EGFR monoclonal antibody cetuximab is the only target drug that has been approved by the US FDA in the treatment for HNSCC.CDKN2A, a tumor-suppressor gene which encodes the cell cycle regulator p16INK4a, has been extensively investigated to be associated with HNSCC." (PMID 33456497, 2020).
tumor (continued). "This supports the hypothesis that genetic factors other than EXT1 or EXT2 mutations, such as CDKN2A, are involved in tumor progression." (PMID 32295254, 2020). "Tumor incidence data in congenic strains carrying the resistance alleles of Cdkn2a and Mtor led us to hypothesize that drug combinations affecting these pathways are likely to have an additive, if not synergistic effect in inhibiting tumor cell growth." (PMID 32923678, 2020). "Nevertheless, the virus contributes to tumor initiation and clonal expansion of infected lymphoid and epithelial cells by inducing specific genetic/epigenetic changes (such as c-myc translocation and loss of CDKN2A/p16) or impairing host immune system." (PMID 32528868, 2020). "Another study, searching to validate tumor drivers and therapeutic targets, found CDKN2A to be mutated in 45% of 40 primary cSCC (20 well-differentiated and 20 moderately/poorly differentiated tumors), from both immunosuppressed and immunocompetent patients, by employing whole-exome analyses." (PMID 32674318, 2020). "This suggests that either a pre-existing clone with a homozygous deletion or a second loss event was selected for as the tumor established itself in this new environment, supporting CDKN2A loss as a late event that may be relevant in the metastatic setting." (PMID 32313009, 2020). "As result, MPM is characterized by a low mutational burden and a genomic landscape dominated by inactivation of several tumor suppressors genes, such as cyclin-dependent kinase inhibitor 2A (CDKN2A), BRCA1 associated protein (BAP1) and neurofibromatosis 2 (NF2)." (PMID 36046389, 2020). "For example, a conditional loss of the INK4a/ARF (CDKN2A) locus generated more rapid development of PanIN lesions, decreased tumor latency, a more undifferentiated histology, and the dissemination of metastatic lesions to the liver and lungs in the LSL-KRASG12D background." (PMID 32456018, 2020). "Homozygous loss of CDKN2A/CDKN2B locus at chromosome 9p21.3 was identified in one tumor." (PMID 32726920, 2020). "In fact, the association of high mutational burden and CIN with short PFS remained as a trend in multivariable Cox models that combined mutational burden, CIN, co-occurring CCND1 and CDKN2A mutations, tumor site, and HPV status (with p = 0.079 and p = 0.059, respectively)." (PMID 30934880, 2019). "Importantly, the MITF‐low/proliferative subtype, characterised by an absence of the expression of immune‐response genes, had only BRAF/NRAS‐mutated samples and more tumours with CDKN2A deletions, and was significantly associated with a poorer prognosis." (PMID 30511391, 2019). "Notably, only tumor cell explants with a BRAFV600E-mutated background harboring loss of CDKN2A expression in combination with TERT promoter mutation developed into stable, immortalized cell lines." (PMID 31391125, 2019). "Loss of the CDKN2A/B locus was observed in one tumor each grouping with HGNET-MN1 and EPN-RELA." (PMID 30876455, 2019). "RASSF1A inactivation may alter the cell cycle in both tumor types, whereas hypermethylation of CDKN2A and inhibition of CDKN1B and CDKN2C caused by MEN1 loss are characteristic of PanNETs." (PMID 30657883, 2019).
tumor (continued). "In adjusted analysis using a multivariable Cox proportional hazards model, AJCC pathologic tumor stage (HR: 1.86; 95% CI: 1.06–3.26), receipt of chemotherapy (HR: 1.87; 95% CI: 1.12–3.12), and CDKN2A copy number loss (HR: 1.42; 95% CI: 1.01–2.00) remained significant." (PMID 29670856, 2018). "Interestingly, despite the proposed tumour suppressor role of inactivating mutations in CDKN2A we consistently observed upregulation of CDKN2A gene expression in the GEP data sets and in our cell lines." (PMID 30202019, 2018). "These CNAs included the loss of CFA22 within RB1 (retinoblastoma tumor suppressor) gene in both tumors, and the loss of CFA26 within PTEN (phosphatase and tensin homologue) gene associated with the loss of a region of CFA11, including CDKN2A (cyclin-dependent kinase inhibitor 2A) in the Dog_2 tumor." (PMID 30514258, 2018). "Indeed, BALB/c mice carry an allelic variant of Cdkn2a that leads to compromised p16 activity, likely causing an increased susceptibility to develop certain tumours." (PMID 29731980, 2018). "The acquisition of additional genetic changes, such as TERT promoter mutations and CDKN2A homozygous deletions, may play a role in tumor progression." (PMID 29739933, 2018). "However, since most of the tumors analyzed in the present study belonged either to the luminal A or the luminal B subtype, our results only can give a hint that hypermethylation of CDKN2A exon 2 is associated with the molecular subtype of the tumor." (PMID 28403857, 2017). "CDKN2A is a tumor-suppressor gene encoding for the p16ink4a protein." (PMID 28445153, 2017). "Similarly, LNT tumor (#461) induced by a lower fiber dose (1 μg versus 2.5 μg) displayed loss of p16 and p19 protein expression, a reduction in Cdkn2a mRNA, and allelic loss of p19Arf." (PMID 29112861, 2017). "CDKN2A (cyclin-dependent kinase inhibitor 2A) is a tumor suppressor gene encoding the p16 and p14." (PMID 28947997, 2017). "In our present study containing only HPV-negative HNSCC tumours, we found a moderate but highly significant downregulation of p16INK4a suggesting rather expressional downregulation than complete loss or silencing of the CDKN2A gene." (PMID 29097782, 2017).
tumor (continued). "Collectively, these findings further suggest that loss of key tumour suppressor genes at the CDKN2A/B locus contributes towards senescence bypass and, additionally, may point towards haploinsufficiency contributing to abrogation of senescence pathways." (PMID 27169376, 2016). "However, only 3 patients within this initial study were identified as thalamic, of which one co-occurred with H3K27M and another with CDKN2A deletion, potentially predisposing to tumour transformation." (PMID 27577993, 2016). "Type I is associated with MET alterations, whereas Type II tumours are characterized by cyclin-dependent kinase Inhibitor 2A (CDKN2A) silencing, SETD2 mutations, transcription factor E3 (TFE3) fusions and increased expression of the nuclear factor-like 2 (NRF2)–antioxidant response element pathway." (PMID 27092491, 2016). "The TSG CDKN2A is located in this region and is mutated in numerous tumor types." (PMID 26205786, 2016). "In addition, mutations in cell cycle genes including those in Rb and CDKN2A were identified in 3 tumor samples (#5, 8 and 16)." (PMID 26068980, 2015). "This suggests that the tumor cells with loss of CDKN2A had a selective growth advantage in vivo." (PMID 25952750, 2015). "We previously reported significant tumor risk allele PAI for the CDKN2A missense SNP rs3731249." (PMID 26575185, 2015). "We recently reported that the CDKN2A missense SNP rs3731249 shows tumor selection of the risk allele in heterozygote cases with somatic CDKN2A loss, with 14 patients with preferential retention of the risk allele versus only 3 with retention of the protective allele." (PMID 26575185, 2015). "Targeted sequencing of the primary tumor revealed deletions of CDKN2A and CDKN2B, a nonsense mutation in ARID2, and single missense mutations of unknown significance in nine other genes." (PMID 26634163, 2015). "In addition to stage III, early recurrence was associated with loss of RUNX3 and CDKN2A, both of which are known tumor suppressor genes in CRC and previously reported to be associated with clinical outcome in CRC." (PMID 25879218, 2015). "The inducible expression vectors of CDKN2A/p16-wild-type and CDKN2A/p16-A148T utilized in the study could be useful for further investigation into whether this somatic mutation can alter the tumor suppression functions of CDKN2A/p16." (PMID 24944698, 2014). "Therefore, high level of p16/CDKN2A expression serves as a specific diagnostic biomarker for tumor infected with high-risk HPV." (PMID 24804233, 2014). "Whole exome sequencing performed in tumor tissue obtained at the time of progressive disease demonstrated a somatic gain-of-function PIK3CA mutation (H1047R) as well as a CDKN2A aberration, which may have contributed to eventual resistance to treatment." (PMID 23470635, 2013). "However, for HC2a/HC3a tumors the frequency of CDKN2A deletions was drastically increased, suggesting that acquisition of CDKN2A deletions occurs later during tumor progression than for example FGFR3 mutations and 9q deletions." (PMID 22685613, 2012). "The causes of the overexpression in the tumor cells might resulted from genetic abnormalities, viral effect or a tumor-associated mutant of CDKN2A." (PMID 22619677, 2012). "The absent expression of p16INK4 in the tumor cells, however, might be caused by homozygous loss of CDKN2A gene as demonstrated in this study or hypermethylation of the CDKN2 promoters as seen in other tumor types." (PMID 22619677, 2012). "Deletion of CDKN2A is associated with poor tumor outcome in patients and mice." (PMID 22046342, 2011).
tumor (continued). "The Cdkn2a locus encodes two tumour suppressors, P16INK4a and P19ARF." (PMID 17598916, 2007). "However, the increased expression of CDKN2a gene products alpha (p16INK4A) and beta (p14ARF) has been described to be associated with progression and unfavourable prognosis in different tumour types." (PMID 17117177, 2006). "Reasoning that silencing or mutating Cdkn2a might facilitate in vitro immortalization as it does for other normal and transformed cells, we used in vivo Crispr/Cas9-mediated targeting of Cdkn2a’s exon 2 at the time of tumor initiation." (PMID 41440033, 2025). "In addition, CDKN2A exon 2 hypermethylation was associated with the molecular subtype of the tumor." (PMID 40649906, 2025). "CDKN2A is a known tumor suppressor, and its loss may render sensitivity to CDK4/6 inhibitors." (PMID 40361368, 2025). "Notably, in NF1-related MPNSTs, the loss of CDKN2A may act synergistically with epigenetic silencing and mechanical restructuring at the cellular level, enhancing tumor heterogeneity and drug resistance." (PMID 40630199, 2025). "Assessment of molecular alterations such as CDKN2A/B hemizygous loss may also be dependent on the assays used and tumor purity of samples, though we approached these analyses as representative of real-world sequencing methodologies implemented in clinical practice." (PMID 39584448, 2025). "Additionally, CDKN2A promotes apoptosis and senescence and inhibits cancer-associated processes like cell-in-cell structure formation and anchorage-independent growth, while it modulates anti-tumor immunity by influencing immune-cell infiltration." (PMID 38666907, 2024). "Similarly, CDKN2A, an important tumor-driving gene, is specifically mutated in cluster 12 in LUAD." (PMID 37390335, 2023). "Interestingly, we found that CDKN2A expression was significantly associated with tumor immune-related pathways such as the TNFA signaling pathway via NFKB, IFN-α response, IFN-γ response, allograft rejection pathway and inflammatory response, especially in BLCA, CESC, MESO, OV, TGCT and THCA." (PMID 36961395, 2023). "As a result of their down-regulated expression, the tumor suppressor genes encoding p16INK4a (cyclin-dependent kinase inhibitor 2A), RASSF1A (RAS association domain family 1 isoform A), and p16INK4b (RAS association domain family 1 isoform B) may play a significant role in tumorigenesis." (PMID 37628989, 2023). "Therefore, we can conclude that under tumor conditions, CDKN2A faces epigenetic modifications to hinder its expression and only CDKN2A with loss-of-function mutations is highly expressed in the tumor tissue and that collectively results in a poor clinical outcome." (PMID 37626750, 2023). "Thus, we support the hypothesis that the CDKN2A gene mutation contributes to uncontrolled tumor proliferation." (PMID 37623944, 2023).